XRCC1 (X-ray repair cross complementing 1)
Diseases named in the same sentence as XRCC1 in open-access papers (continued):
Sharing a sentence is not in itself a finding about the gene and the disease.
colorectal adenoma (3 papers, 2006 to 2015). An adenoma that arises from the colon or rectum. "The XRCC1 399Gln allele has been linked with a reduced risk of colorectal adenomas, and XRCC1 has also been associated with improved progress in patients who underwent chemotherapy, but not in those who received surgery alone." (PMID 18823566, 2008). "As far as we know, the KAM study is the first reporting an association between the XRCC1 Arg280His polymorphism and colorectal adenoma and carcinoma risk." (PMID 16542436, 2006). "In the present study we used a case-control design to test the association between five amino acid substitution variants of DNA repair genes, XRCC1 (Arg194Trp), XRCC1 (Arg280His), XRCC1 (Arg399Gln), XRCC3 (Thr241Met) and XPD (Lys751Gln), and colorectal adenoma/cancer risk in a Norwegian cohort." (PMID 16542436, 2006).
dermatitis (3 papers, 2013 to 2020). An inflammatory process affecting the skin. "The XRCC1 399Arg/Gln was significantly associated with the development of grade 3 dermatitis (Odds Ratio, 2.65; 95% CI, 1.04–6.73; p = 0.037, χ2 = 4.357)." (PMID 23375119, 2013).
differentiated thyroid carcinoma (3 papers, 2013 to 2017). Differentiated thyroid carcinoma (DTC), also known as papillary or follicular thyroid carcinoma, is a slow-growing malignancy usually presenting in adults as an asymptomatic thyroid mass. "As Yan and collaborators showed, the XRCC1 variant can interact with the XRCC3 variant to significantly increase differentiated thyroid carcinoma (DTC) susceptibility." (PMID 29178884, 2017).
endometrial carcinoma (3 papers, 2012 to 2024). A malignant tumor arising from the epithelium that lines the cavity of the uterine body. "Gene-gene interaction between the ERCC2 751Gln and XRCC1 194Trp variants also increased the risk of endometrial cancer (OR 4.41; 95 % CI 2.01–9.67)." (PMID 22544315, 2012). "The 751 Lys/Gln polymorphism of the ERCC2 gene may be linked with endometrial cancer occurrence and its effect can be potentiated by variants of the XRCC1 gene or first degree relatives positive cancer history." (PMID 22544315, 2012).
gallbladder cancer (3 papers, 2020 to 2022). "We found that XRCC1 positive expression was associated with several poor clinicopathological features of gallbladder cancer." (PMID 32426369, 2020). "The ROC curves suggested that XRCC1 expression had potential clinicopathological diagnostic value in gallbladder cancer." (PMID 32426369, 2020). "We found that XRCC1 was significantly up-regulated in gallbladder cancer in protein and mRNA levels." (PMID 32426369, 2020). "Positive XRCC1 expression was correlated with aggressive clinicopathological features and was an independent poor prognostic factor in gallbladder cancer." (PMID 32426369, 2020). "We then assessed XRCC1 expression in gallbladder cancer tissues (including 69 SC/ASCs and 146 ACs) and gallbladder epithelium with chronic cholecystitis by immunohistochemistry." (PMID 32426369, 2020). "In this study, we investigated the expression of XRCC1 and its clinicopathological and prognostic significance in gallbladder cancer, and explored the biological role of XRCC1 in gallbladder cancer cells." (PMID 32426369, 2020). "In conclusion, this study demonstrated that XRCC1 was overexpression in gallbladder cancer tissues." (PMID 32426369, 2020). "Thus, this study indicates that XRCC1 may be a promising predictive biomarker of gallbladder cancer and a potential therapeutic target for gallbladder cancer." (PMID 32426369, 2020). "Gallbladder cancer patients (both AC/ASC and AC) in XRCC1 positive expression group had significantly shorter average survival time than patients in the negative expression group (all P < 0.01)." (PMID 32426369, 2020). "XRCC1 is involved in tumorigenesis, progression, and chemo-resistance of several human cancers, but the role of XRCC1 in gallbladder cancer is never reported." (PMID 32426369, 2020). "However, there is no study reporting the function of XRCC1 in gallbladder cancer cells." (PMID 32426369, 2020).
ischemic stroke (3 papers, 2006 to 2022). A stroke disorder caused by obstruction of blood flow to the brain, due to thrombotic (local blood clot formation) or embolic (due to a blood clot or other material traveling from another site) event. "In conclusion, this study showed that the genetic variant of XRCC1 rs25487 was associated with a decreased risk of ischemic stroke." (PMID 27763529, 2016). "We studied two common polymorphisms in the DNA repair gene, XRCC1, C26304T and G28152A, in 134 well characterized patients with non lacunar ischemic strokes." (PMID 17087834, 2006). "Furthermore, impaired XRCC1 was associated with increased genetic susceptibility to ischemic stroke." (PMID 36712419, 2022). "Further investigations of the XRCC1 gene as a modifier of the cerebral response in ischemic stroke in a larger sample size are needed to confirm and expand on these results." (PMID 17087834, 2006).
laryngeal tumor (3 papers, 2011 to 2023). "There were not significant associations between XRCC1 Arg194Trp polymorphism with HNSCC risk based on pharyngeal or laryngeal tumor sites under different genetic models (p values >.001)." (PMID 36573562, 2023).
neuroblastoma (3 papers, 2014 to 2018). Neuroblastoma (NB) is the most common solid, extracranial childhood tumor. "Last, our work lacks of in vitro data to support a role for these XRCC1 polymorphisms in neuroblastoma, which should be completed in the future." (PMID 30362960, 2018). "Give the significant role of XRCC1 in DNA repair, we conducted a case-control study to explore the association between XRCC1 polymorphisms and risk of neuroblastoma." (PMID 30362960, 2018). "Stratified analysis revealed that the XRCC1 rs25489 CT/TT was strongly associated with reduced risk of neuroblastoma in the children ≤ 18 months of age and subgroup with clinical stage I+II+4s diseases, compared with CC genotypes." (PMID 30362960, 2018). "In this two-center Chinese population study, we examined the impact of polymorphisms in the XRCC1 gene on neuroblastoma susceptibility." (PMID 30362960, 2018). "Our study helps to provide novel insight into the role of XRCC1 gene polymorphisms in neuroblastoma risk." (PMID 30362960, 2018). "Herein, we conducted a case-control study with 393 neuroblastoma patients and 812 controls to explore the association of XRCC1 gene polymorphisms (rs1799782 G>A, rs25487 C>T, rs25489 C>T and rs915927 T>C) with neuroblastoma risk." (PMID 30362960, 2018). "Stratification analysis of XRCC1 rs25489 C>T polymorphism and combined risk genotypes with neuroblastoma susceptibility." (PMID 30362960, 2018). "In conclusion, we report that polymorphisms in XRCC1 gene may exert a low-penetrant effect on neuroblastoma risk in Chinese population." (PMID 30362960, 2018). "Association between XRCC1 gene polymorphisms and neuroblastoma susceptibility." (PMID 30362960, 2018). "More evidence of the association between XRCC1 gene polymorphisms and neuroblastoma risk is needed." (PMID 30362960, 2018). "Failure to detect the association between XRCC1 polymorphisms and neuroblastoma risk might be due to the small sample size and the low-penetrant effect of common polymorphisms." (PMID 30362960, 2018). "However, the contribution of XRCC1 gene polymorphisms to neuroblastoma risk remains unclarified." (PMID 30362960, 2018). "We found that XRCC1 polymorphisms might play a low-penetrant role on the neuroblastoma risk." (PMID 30362960, 2018). "Cerebellar granule cells from Xrcc1 heterozygous mice and Xrcc1 knockdown in human neuroblastoma cells show an accumulation of SSB and reduced survival following oxidative stress." (PMID 26942017, 2016). "This could be because the expression of the SP-BER component XRCC1 is totally ablated in differentiated neuroblastoma cells, while being only partially downregulated in our neurons." (PMID 25032865, 2014).
open-angle glaucoma (3 papers, 2011 to 2023). Chronic outflow obstruction of the eye's drainage canals that can lead to increased internal eye pressure and optic nerve damage. "Furthermore, the 399 Arg/Gln genotype of the X-ray repair cross-complementing group 1 (XRCC1) gene is associated with poor DNA repair ability and is related to an increased risk of primary open-angle glaucoma (POAG) occurrence and progression." (PMID 36835325, 2023). "At present, multiple genesand genetic loci that lead to glaucoma have been found, most of which are related toprimary open angle glaucoma (POAG).There are reports that suggest an association among the hOGG1, APE1and XRCC1 genes and a susceptibility to oesophageal, breast andbladder cancer." (PMID 28396513, 2017).
primary open angle glaucoma (3 papers, 2007 to 2017). "Distribution of allele and genotype frequency of XRCC1-Arg399Gln and XPD-Lys751Gln polymorphisms in glaucoma patients and healthy controls." (PMID 17242676, 2007). "In addition till date all the association studies of XRCC1 or XPD polymorphisms with glaucoma have not analyzed the data along the lines of gender or ethnic background." (PMID 21617750, 2011). "We propose that although the XRCC1 polymorphisms might not directly participate in causing glaucoma but it can act as a hypomorph and thus could be involved in accelerating the progression of the DNA damage in the latter stages of the disease by hindering the DNA repair mechanism in male patients." (PMID 21617750, 2011).
pterygium (3 papers, 2010 to 2018). A wedge-shaped fibrovascular lesion arising from the bulbar conjunctiva and extending to the cornea. "The multiple logistic regression analysis showed that the XRCC1 genotype is related to the risk of pterygium after adjusted with hOGG1 and APE1 polymorphisms." (PMID 20577654, 2010). "This is because the polymorphisms of XRCC1 and hOGG1 have a different DNA repair capacity, and people who have polymorphism with lower DNA repair activity are prone to pterygium." (PMID 20431719, 2010). "In our study, we found that the XRCC1 codon 194 polymorphism was associated with a decreased risk of developing pterygium, and that the codon 399 polymorphism was associated with susceptibility to pterygium." (PMID 20431719, 2010). "In the present study, we conducted a case control study to evaluate the associations of pterygium formation and XRCC1 codon 107, 194, 280, and 399; XPA A23G; XPA codon 228; and XPD codon 751 polymorphisms." (PMID 20431719, 2010). "The XRCC1 codon 194 polymorphism causes a decreased risk of developing pterygium, but the codon 399 polymorphism increases the risk." (PMID 20431719, 2010). "Our finding of a positive association between the XRCC1 codon 399Gln allele and pterygium is consistent with the published, functional studies." (PMID 20431719, 2010). "The analysis of the polymorphisms located at XRCC1 codon 399 in pterygium showed that 31 (37.3%) were homozygous for the A/A genotype, 17 (20.5%) were homozygous for the G/G genotype, and 35 (42.2%) were heterozygous for the A/G genotype." (PMID 20577654, 2010). "In conclusion, our study demonstrated for the first time that the XRCC1 codon 194 polymorphism is inversely associated with pterygium, and that the codon 399 polymorphism is associated with the risk of pterygium." (PMID 20431719, 2010). "Subjects who were heterozygous or homozygous for the variant allele (399Glu) of XRCC1 appeared to experience a higher risk of pterygium than those who were homozygous for the wild-type allele (399Arg) (OR: 1.758; 95% CI: 1.038–2.980, p=0.036)." (PMID 20577654, 2010). "Genotypes and allelic frequencies for XRCC1 codon 399 polymorphism (G→A, Arg399Gln) in the pterygium and control group." (PMID 20431719, 2010). "For example, polymorphism of X-ray repair cross complementary 1 (XRCC1) gene might lead to decreased chance of pterygium development." (PMID 31565648, 2018). "In conclusion, XRCC1 Arg399Glu is correlated with pterygium and might become a potential marker for the prediction of pterygium susceptibility." (PMID 20577654, 2010). "The multiple logistic regression analysis of XRCC1 (Arg399Gln), hOGG1 (Ser326Cys),and APE1 (Asp148Glu) genotypes and the risk of pterygium." (PMID 20577654, 2010). "Because the polymorphism of hOGG1 was reported to be associated with pterygium, it is logical to assume the correlation between XRCC1, XPA, and XPD polymorphisms and pterygium formation." (PMID 20431719, 2010). "This is the first case-control study of polymorphisms in XRCC1 codon 107, 194, 280, and 399; XPA A23G; XPA codon 228; and XPD codon 751 in relation to pterygium formation." (PMID 20431719, 2010). "If pterygium is associated with reduced activity of the BER system, it is reasonable that the XRCC1 and hOGG1 polymorphisms were found to be differently distributed between those with pterygium and the normal controls." (PMID 20431719, 2010). "Our study revealed that the XRCC1 (Arg399Glu) polymorphism is associated with susceptibility to pterygium, but the hOGG1 (Ser326Cys) and APE1 (Asp148Glu) are not." (PMID 20577654, 2010). "XRCC1 (Arg399 Glu) is correlated with pterygium and might become a potential marker for the prediction of pterygium susceptibility." (PMID 20577654, 2010). "Second, we could not show that the AA polymorphism of XRCC1 codon 399 created a significant risk of developing pterygium (OR=2.513; 95% CI: 0.792–7.969)." (PMID 20431719, 2010).
pterygium (continued). "Genotype distribution of XRCC1 (Arg399Gln), hOGG1 (Ser326Cys) and APE1 (Asp148Glu) genes among pterygium patients and control group." (PMID 20577654, 2010). "Therefore, the aim of this study was to determine the relationship between XRCC1 (Arg399Gln), hOGG1 (Ser326Cys), and APE1 (Asp148Glu) SNPs and pterygium." (PMID 20577654, 2010).
schizophrenia (3 papers, 2016 to 2018). A major psychotic disorder characterized by abnormalities in the perception or expression of reality. "This (hypothetical) relation offers a potential rationale to consider the XRCC1 as a ‘candidate susceptibility gene’ for schizophrenia." (PMID 26824244, 2016). "The present study will be the first report on the existence of a significant association between Arg399Gln of XRCC1 and schizophrenia from Indian population." (PMID 26824244, 2016). "Intriguingly, genetic polymorphisms in the core BER-protein XRCC1 itself, or in XRCC1 interacting proteins such as Ogg1, have been repeatedly implicated in schizophrenia and ASD." (PMID 27258260, 2016). "It is at this juncture, that we present the results of our study on the frequency distribution of the SNP (Arg399Gln; rs25487) of XRCC1 in Tamil population, and its association with schizophrenia." (PMID 26824244, 2016). "Although the SNPs at the serotoninergic and dopaminergic systems were suggested to have asignificant association with the disease, not much was known of the association between the polymorphism(s) at XRCC1 locus and schizophrenia." (PMID 26824244, 2016). "Using this approach, they showed that Nes-Cre driven ablation of XRCC1 in the CNS leads to impaired development of the cerebellum and hippocampus, two brain regions strongly implicated in neurodevelopmental disorders such as schizophrenia and ASD." (PMID 27258260, 2016). "These interactions existing between schizophrenia and smoking behaviour, and the polymorphism in question have given us compelling reasons to examine if there exists any significant association between the aberrant XRCC1 and smoking behaviour, leading to schizophrenia." (PMID 26824244, 2016). "The interest on the XRCC1 protein related to schizophrenia has been evolved out of its profuse presence (and the predominant mRNA levels) in the brains of rats and baboons." (PMID 26824244, 2016). "The question as to how mechanistically the aberration in XRCC1 could contribute to the pathophysiology of schizophrenia is still enigmatic." (PMID 26824244, 2016). "An interaction involving the SNP(s) of DNA repair system (XRCC1, for example) and increased apoptosis of nerve cells seems to exist, which in turn could play a vital role in the onset of several neuropsychological disorders, including schizophrenia." (PMID 26824244, 2016).
Thrombocytopenia (3 papers, 2011 to 2024). A reduction in the number of circulating thrombocytes. "In keeping with this, XRCC1 rs25487 was identified as risk factors for grade 3-4 leukocytopenia in recessive model (OR = 2.841; 95% CI: 1.051–7.681; p = 0.040), grade 3-4 thrombocytopenia in additive model (OR = 2.033; 95% CI: 1.113–3.715; p = 0.021) in discovery cohort of 437 NSCLC patients." (PMID 39234108, 2024).
acute lymphoblastic leukemia (2 papers, 2012 to 2022). Leukemia with an acute onset, characterized by the presence of lymphoblasts in the bone marrow and the peripheral blood. "Recently, there have been a number of studies on the association between XRCC1 polymorphisms and childhood acute lymphoblastic leukemia (ALL) risk." (PMID 22529951, 2012).
Anxiety (2 papers, 2022 to 2023). Intense feelings of nervousness, tension, or panic often arise in response to interpersonal stresses. "To investigate the effect of increased DNA damage caused by XRCC1 KO in the forebrain on affective behaviours, we evaluated the impact of XRCC1 KO on measures of innate anxiety-like behaviour using the light–dark box (LDB) and the open field tests." (PMID 35907861, 2022). "Our results uncover a previously unappreciated connection between the DNA repair protein XRCC1, unrepaired DNA damage in the forebrain and a sex-specific anxiety-like phenotype." (PMID 35907861, 2022). "Future investigations of the possible link between XRCC1, DNA damage and innate anxiety and fear will help to gain more insight into the intricate mechanisms whereby accumulating DNA damage can influence complex brain and behavioural functions." (PMID 35907861, 2022). "In view of our behavioural findings in the XRCC1 KO mice, we examined GABAergic markers in the amygdala and in the hippocampus, both of which regions are believed to critically modulate both innate anxiety and learned fear." (PMID 35907861, 2022). "Using a novel and selective model of XRCC1 KO in mice, our study is the first to demonstrate a role of unrepaired DNA damage in the forebrain in the modulation of innate anxiety and learned fear in a sex-dependent manner." (PMID 35907861, 2022). "While motor coordination, cognition and social behaviour remained unchanged, XRCC1 KO in the forebrain caused increased anxiety-like behaviour in males, but not females, as assessed by the light–dark box and open field tests." (PMID 35907861, 2022). "To test whether a forebrain-specific XRCC1 KO may also modulate conditioned forms of anxiety/fear, we compared KO and control animals in the cued (Pavlovian) fear conditioning test and the contextual fear extinction test." (PMID 35907861, 2022). "Concluding, these results suggest that XRCC1 KO in the forebrain induces an increase in anxiety-related behaviour in male, but not female animals." (PMID 35907861, 2022).
astrocytoma (2 papers, 2016 to 2021). "Moreover, the C alleles of CHAF1A rs243341 and rs2992 as well as the T allele of XRCC1 rs25487 were associated with a decreased risk of astrocytoma subtype." (PMID 27613841, 2016). "Furthermore, polymorphisms in CHAF1A and XRCC1 are associated with the risk of astrocytoma, whereas SNPs in EME1, ATM, GLTSCR1, and XRCC4 are associated with susceptibility to non-astrocytoma subtypes." (PMID 27613841, 2016). "Moreover, a decreased risk of astrocytoma subtype associated with the C alleles of CHAF1A rs243341 and rs2992 as well as the T allele of XRCC1 rs25487 involved in DNA repair pathway was detected (pDOM=0.040, pDOM=0.049, and pDOM=0.033, respectively)." (PMID 27613841, 2016).